RFX6 (regulatory factor X6)
Diseases named in the same sentence as RFX6 in open-access papers (continued):
Sharing a sentence is not in itself a finding about the gene and the disease.
insulinoma (1 paper, 2022). "All these comparisons highlighted several genes regulated only by NeuroD1, such pax4, rfx6, insm1a/b, genes reported to be direct targets of Neurod1 in human insulinoma cell line, therefore validating our experiments." (PMID 35286299, 2022).
Obesity (1 paper, 2021). Accumulation of substantial excess body fat. "High-fat diet (HFD)-induced obesity in mice reduces gene expression of Etv1, Isl1, Mlxipl, Nkx2.2 and Rfx6 whereas Cck, Gip and Pyy, Gcg gene expression is not impacted." (PMID 33037328, 2021).
prostate tumors (1 paper, 2024). "Elevated RFX6 expression was also noted in prostate tumors relative to paired normal tissues." (PMID 38932472, 2024).
cancer (7 papers, 2020 to 2024). A tumor composed of atypical neoplastic, often pleomorphic cells that invade other tissues. "MAFB and GPR68 genes are downregulated interactors of RFX6 that Swiss-Prot associates with cancer." (PMID 34715892, 2021). "We signalled the interactors of RFX6 with other up and downregulated genes, that may be interested in severity of diabetic condition, in multi-organs impairment and cancer predisposition." (PMID 34715892, 2021). "Based on our ChIP‐seq and metabolome profiling, KEGG analysis found that central carbon metabolism in cancer was one of the pathways potentially regulated by RFX6." (PMID 38093528, 2023). "Although regulatory factor X6 (RFX6) is aberrantly expressed in different cancers, its precise role in cancer development remains ambiguous." (PMID 38093528, 2023). "Previous studies have highlighted the linkage between the aberrant RFX6 expression and cancer development." (PMID 38093528, 2023). "It is worth noting that the high expression of RFX6 was positively correlated with EMT pathways in cancer, namely, the NF-kB and JAK–STAT pathway." (PMID 34988028, 2021). "The gene regulatory factor 6 (RFX6) is a transcription factor that is involved in cancer progression in various cancers." (PMID 32564007, 2020). "In addition, RFX6 was found to regulate the number of pancreatic progenitors, suggesting its potential involvement in cancer stemness." (PMID 32564007, 2020). "The interaction of RFX6 with other upregulated genes, such as EIF2AK3, may induce a severe diabetic condition and could be related to multi-organ impairment and cancer degeneration." (PMID 34715892, 2021).
tumor (6 papers, 2020 to 2024). "This mechanistic understanding enhances our comprehension of RFX6 contributing to PCa cellular aggressiveness and tumor progression." (PMID 38932472, 2024). "Collectively, these findings confirm that HOXA10 mimics the effects of RFX6 on orchestrating aggressive PCa cellular behavior in vitro and tumor growth in vivo." (PMID 38932472, 2024). "In mouse models with prostate‐specific PTEN deletion, RFX6 expression markedly increased in tumor tissues compared to normal prostate." (PMID 38932472, 2024). "In line with the observed phenotype in nude mice, the expression of RFX6 markedly increased the ability of tumor cells to form organoids, accompanied by a substantial alteration in proliferation." (PMID 38932472, 2024). "We further evaluated the impact of HOXA10 on RFX6‐driven PCa tumor progression using luciferase‐labeled 22Rv1 cells in SCID mice." (PMID 38932472, 2024). "In a subcutaneous xenograft model, RFX6 overexpression profoundly enhanced tumor growth, but this effect was significantly reduced with HOXA10 knockdown." (PMID 38932472, 2024). "The results showed that tumors derived from RFX6 overexpressing group exhibited significantly faster growth rates and markedly higher tumor weights compared to the control group." (PMID 38932472, 2024). "To determine the effect of RFX6 on tumor growth in vivo, we conducted an experiment by subcutaneously implanting 22Rv1 cells, with either enforced RFX6 expression or an empty vector, into nude mice." (PMID 38932472, 2024). "The notable correlation observed between RFX6 and AR expression in PCa tissues underscores the importance of their interplay in influencing tumor growth and development." (PMID 38932472, 2024). "Specifically, glucose and lactate levels were significantly diminished in tumours from the RFX6‐KO group while being elevated in the RFX6‐OE group, which was consistent with previous results." (PMID 38093528, 2023). "In the GSE54236 dataset, the RFX6‐high expression group were more likely to double the tumour size than the RFX6‐low expression group." (PMID 38093528, 2023). "Subcutaneous models revealed that silencing PGAM1 suppressed the RFX6‐induced cell proliferation in vivo, presenting as attenuated tumour volumes, tumour weights and Ki67+ cells in the stable PGAM1‐KD groups." (PMID 38093528, 2023). "Concurrently, this study also exhibited that RFX6 expression was inversely correlated with the dysfunction of progressive T cell, suggesting its functions in reshaping tumour microenvironment." (PMID 38093528, 2023). "Microarrays of HCC tissues were employed to investigate the expression of RFX6 in tumour and adjacent non‐neoplastic tissues." (PMID 38093528, 2023). "IHC staining of the tumour tissues also demonstrated an increased number of positive cells for Ki67 in the RFX6‐OE group." (PMID 38093528, 2023). "In conclusion, our study recognised RFX6 as an essential gene for tumour development and uncovered its effect on HCC progression." (PMID 38093528, 2023). "Tumours of the RFX6‐OE group exhibited an evidently higher level of [18F]‐FDG uptake than the control group, illustrating that RFX6 promoted the glucose consumption in HCC cells in vivo." (PMID 38093528, 2023). "In the subcutaneous models, the comparison of growth curves and tumour weights found that RFX6‐KO markedly inhibited the xenograft tumour growth." (PMID 38093528, 2023). "In a subsequently constructed orthotopic xenograft model, the RFX6‐OE group showed a larger tumour burden than the vector group." (PMID 38093528, 2023). "Due to the possible role of RFX6 in tumor immune response, we estimated the immune infiltration with CIBERSORT." (PMID 34988028, 2021). "Knockdown of RFX6, by contrast, got the opposite results of suppression of tumor cell migration and invasion." (PMID 34988028, 2021).
tumor (continued). "Six characteristic genes (IQCE, RFX6, GPAA1, BAHCC1, CLEC2B, and AGAP2) were selected by random forest feature selection, many of which have been reported to be associated with tumor progression." (PMID 32462000, 2020). "Moreover, combining RFX6 knockdown with enzalutamide treatment led to even further decreases in tumor volume and weight." (PMID 38932472, 2024). "However, the group with RFX6 knockdown exhibited a notable reduction in both tumor volume and weight compared to the control group." (PMID 38932472, 2024). "Lentivirus‐mediated RFX6 knockdown in 22Rv1 cells resulted in a notable decrease in cell growth, viability, colony formation, and migratory and invasive capabilities compared to control shRNA‐treated cells, consistent with our previous findings using siRNA‐mediated RFX6 tumor cell biology assays." (PMID 38932472, 2024). "Moreover, metabolite levels showed that silencing PGAM1 markedly suppressed the RFX6‐induced glycolysis in vivo, presenting as attenuated lactate and 2‐PG production in the subcutaneous tumours from the stable PGAM1‐KD groups." (PMID 38093528, 2023). "IHC staining of the tumour tissue revealed a marked reduction in Ki67+ cells by silencing RFX6." (PMID 38093528, 2023). "Further, RFX6 exerted a tumour‐promoting effect on HCC growth and metastasis." (PMID 38093528, 2023). "IHC staining of tumour tissues from previous models also showed the decreased expression of PGAM1 in the RFX6‐KO cells and increased expression in the RFX6‐OE cells in vivo, supporting the transcriptional regulation of PGAM1 by RFX6 in HCC cells." (PMID 38093528, 2023). "In the retrospective analysis of the metabolome profiling data from tumour tissues, levels of 2‐PG, phosphoenolpyruvate and pyruvate, which were downstream products of PGAM1, were observed to decrease in the RFX6‐KO group and increase in the RFX6‐OE group." (PMID 38093528, 2023). "Moreover, RFX6 expression displayed a stepwise increase from no recurrence to distant metastasis stage, linking to tumour aggressiveness." (PMID 38093528, 2023). "Furthermore, the chi‐squared test revealed that upregulated RFX6 expression was correlated to the absence of tumour capsules, vascular invasion, adjacent organ invasion and lymphatic metastasis." (PMID 38093528, 2023).
gastrointestinal disorders (1 paper, 2024). "RFX6 is typically expressed in the pancreas and gastrointestinal tract, essential for pancreatic development and insulin production, with its dysregulation implicated in gastrointestinal disorders." (PMID 38932472, 2024).
RFX6 also shares sentences with these, for which no sentence is quoted: exocrine pancreatic insufficiency (2 papers); Alagille syndrome (1); autonomic neuropathy (1); biliary atresia (1); celiac disease (1); cholestasis (1); cleidocranial dysplasia (1); Crigler-Najjar syndrome (1); Dubin-Johnson syndrome (1); epilepsy (1); Fanconi anemia (1); haemochromatosis (1); heart malformation (1); intrauterine growth retardation (1); Kabuki syndrome (1); neurodegenerative disease (1); Onset (1); ovarian insufficiency (1); pancreatic diseases (1); permanent neonatal diabetes mellitus (1); Premature ovarian insufficiency (1); progressive familial intrahepatic cholestasis (1); vitiligo (1); Zimmermann-Laband syndrome (1).